SMIM29 (small integral membrane protein 29)
Synonyms: C6orf1; LBH; MGC57858
Tractability: Antibody: UniProt predicts a signal peptide or a membrane-spanning region.
Gene: Protein-coding gene on chromosome 6 (34,246,381 to 34,249,108, reverse strand). Ensembl gene ENSG00000186577.
Subcellular location: Membrane
Gene Ontology:
Cellular component: membrane
Genetic constraint (gnomAD): Loss-of-function variants: 4 observed, 11.31 expected, observed/expected ratio (o/e) 0.35, 90% interval 0.17 to 0.81. The upper end of that interval is the gene's LOEUF score, 0.81, which puts it in group 3 of 6, group 1 being the genes least tolerant of losing a copy. Missense variants: 122 observed, 125.83 expected, observed/expected ratio (o/e) 0.97, 90% interval 0.84 to 1.13. Synonymous variants: 50 observed, 48.65 expected, observed/expected ratio (o/e) 1.03, 90% interval 0.82 to 1.3.
Homologues: Orthologues: chimpanzee SMIM29 (100% identical), rat Smim29 (97% identical), mouse Smim29 (96% identical), pig SMIM29 (79% identical), dog SMIM29 (75% identical), zebrafish smim29 (56% identical). Paralogues in human: C3orf18 (42% identical).
Diseases named in the same sentence as SMIM29 in open-access papers:
SMIM29 is named in the same sentence as 3 diseases in open-access papers, as found by Europe PMC text mining. Sharing a sentence is not in itself a finding about the gene and the disease. The quoted sentences say what the papers report.
metabolic syndrome (1 paper, 2022). A cluster of metabolic risk factors for CARDIOVASCULAR DISEASES and TYPE 2 DIABETES MELLITUS. "We identified non-synonymous mutations e.g., in ApoM, Notch4, Slc39a7, Smim29 genes and other variations in or near genes associated with metabolic syndrome in human genome-wide association studies." (PMID 36014934, 2022).
Obesity (1 paper, 2022). Accumulation of substantial excess body fat. "The small integral membrane protein 29 (Smim29), showing a predicted missense mutation in the SHR-derived differential segment in BN.SHR20, has been recently associated to several obesity-related indices, type 2 diabetes, fasting insulin, and HDL cholesterol." (PMID 36014934, 2022).
SMIM29 also shares sentences with these, for which no sentence is quoted: type 2 diabetes (1 paper).